MDM4 (MDM4 regulator of p53)
Diseases named in the same sentence as MDM4 in open-access papers (continued):
Sharing a sentence is not in itself a finding about the gene and the disease.
brain tumor (4 papers, 2012 to 2024). "During this procedure, SNUH utilized NGS with a brain tumour-targeted gene panel, identifying the TPM3::NTRK1 fusion, amplification of MDM4/AKT3, and one-copy loss of PTEN/FGFR2, leading to the diagnosis of the tumour as HGG, not otherwise specified (NOS), according to the WHO2021 criteria." (PMID 39014476, 2024).
chronic lymphocytic leukemia (4 papers, 2017 to 2025).
dilated cardiomyopathy (4 papers, 2010 to 2025). Cardiomyopathy which is characterized by dilation and contractile dysfunction of the left and right ventricles.
esophageal cancer (4 papers, 2014 to 2024). A primary or metastatic malignant neoplasm involving the esophagus. "A meta-analysis of 15 studies and over 69,000 subjects found an overall inverse association between MDM4 rs4245739*C and risk for breast, ovarian, endometrial, lung, colon, esophageal cancer, prostate, and non-Hodgkin’s lymphoma." (PMID 37345045, 2023). "Considering the gene-gender interaction of the MDM4 polymorphism, we did find marginal interaction in our previous study on esophageal cancer (Pinteraction = 0.080)." (PMID 25203442, 2014). "Our previous studies also indicated that significantly decreased breast cancer and esophageal cancer risks among carriers of the MDM4 rs4245739 C allele compared with those with the A allele in Chinese." (PMID 25203442, 2014). "In ovarian cancer, retinoblastoma and esophageal cancer cells, miR-191 could selectively bind to the MDM4-C allele mRNA but not the MDM4-A allele mRNA, which resulting in a statistically significant increased expression of MDM4 mRNA and protein among the MDM4 rs4245739 A allele carriers." (PMID 25203442, 2014). "For the paired tumor and adjacent normal specimens, the MDM4 expression of tumor tissue in 7 cancer types was also significantly higher than that in its corresponding adjacent tissues, including BRCA, CHOL, COAD, Esophageal carcinoma (ESCA), HNSC, LIHC, and STAD." (PMID 38281029, 2024).
Ewing sarcoma (4 papers, 2011 to 2021). A small round cell tumor that lacks morphologic, immunohistochemical, and electron microscopic evidence of neuroectodermal differentiation. "As only a maximum 30.5% reduction in MDM4 promoter activity was observed following 4 μM XI-006 treatment, our findings suggest that XI-006 cytotoxicity in Ewing sarcoma cell lines cannot be attributed to repression of MDM4 activity." (PMID 26095524, 2015). "Although XI-006 did not attenuate MDM4 mRNA levels in the sensitive Ewing sarcoma cell line TC252, a 23.1% reduction was observed in WE-68 cells (0.5 μM, 12 hrs), the least sensitive Ewing sarcoma cell line." (PMID 26095524, 2015). "Low micro-molar concentrations of XI-006 induced rapid apoptosis specifically in Ewing sarcoma cell lines (IC50 0.099–1.61 μM) in the absence of both observable DNA damage and effect on MDM4 expression levels." (PMID 26095524, 2015).
gastric cancer (4 papers, 2017 to 2025). A primary or metastatic malignant neoplasm involving the stomach. "Here, we reported a relatively large hospital-based case-control study of 1,077 gastric cancer patients and 1,173 cancer-free controls in an Eastern Chinese population to evaluate associations between three common tagging SNPs of MDM4 and gastric cancer risk." (PMID 28099948, 2017). "We investigated the associations of three tagging SNPs of MDM4 with risk of gastric cancer in this large, ethnic-specific single institutional case-control study." (PMID 28099948, 2017). "We found a significant association of the rs1380576 variant GG genotype in MDM4 with a decreased gastric cancer risk under a recessive genetic model, especially among subgroups of males, never-smokers and subjects with non-cardia cancer." (PMID 28099948, 2017). "In summary, the present study investigated the associations between three MDM4 tagging SNPs and gastric cancer risk with a relatively large sample size." (PMID 28099948, 2017). "In this study of 1,077 gastric cancer (GCa) cases and 1,173 matched cancer-free controls, we investigated associations between three tagging single nucleotide polymorphisms (SNPs) (rs11801299 G>A, rs1380576 C>G and rs10900598 G>T) in MDM4 and gastric cancer risk in an Eastern Chinese Population." (PMID 28099948, 2017). "The observed significantly decreased expression of the MDM4 gene associated with the rs1380576 GG variant genotype may have lead gastric cancer susceptibility in this study population." (PMID 28099948, 2017). "Despite these limitations, our findings are biologically plausible and provide some novel clues for the role of MDM4 in the development of gastric cancer." (PMID 28099948, 2017).
head and neck cancer (4 papers, 2014 to 2024). A primary or metastatic malignant neoplasm affecting the head and neck. "Although some studies have reported associations of some MDM4 genetic variants with HPV-associated head and neck cancers, these studies either defined HPV16 status of study patients by serology or had mixed tumor sites." (PMID 29156829, 2017). "NSC146109 (XI-011), one of small-molecule MDM4 inhibitors, was proven effective in liver, breast, cervical, head and neck cancer." (PMID 38281029, 2024).
gastric adenocarcinoma (3 papers, 2016 to 2024). "Based on these findings, we predict that EBNA1 may be linked to MDM2 and MDM4 expression levels, as well as the risk of developing gastric adenocarcinoma." (PMID 36624687, 2023). "This study evaluates the MDM4 expression in patients with gastric adenocarcinoma (GTAC) at the mRNA and protein levels and examines relationships among MDM4 expression, clinicopathological features, and prognosis." (PMID 27626496, 2016).
hepatoblastoma (3 papers, 2021 to 2023). Hepatoblastoma (HB) is a malignant hepatic tumor and is the most common pediatric liver cancer.
kidney cancer (3 papers, 2021 to 2024). Primary or metastatic malignant neoplasm involving the kidney. "Notably, the alterations in MDM4 expression, have been implicated in certain kidney disorders, such as kidney cancer, AKI, and else." (PMID 38536018, 2024).
meningioma (3 papers, 2023). A generally slow growing tumor attached to the dura mater. "There is currently no information on the percentage of meningiomas that express MDM4." (PMID 37509605, 2023).
non-Hodgkin lymphoma (3 papers, 2014 to 2023). Distinct from Hodgkin lymphoma both morphologically and biologically, non-Hodgkin lymphoma (NHL) is characterized by the absence of Reed-Sternberg cells, can occur at any age, and usually presents as a localized or generalized lymphadenopathy associated with fever and weight loss.
renal cell carcinoma (3 papers, 2021 to 2023). "The abnormal condition of VHL, HIF, MDM2, MDM4, and other genes linked to the development of renal cell carcinoma is closely related to the disappearance of its anticancer function." (PMID 37861516, 2023). "MDM4 mRNA expression was increased in clear cell renal cell carcinomas (ccRCC); as such, it was a prognostic marker and its silencing inhibits the migration and invasiveness of RCC cells." (PMID 36313991, 2022).
serous ovarian cancer (3 papers, 2016 to 2019). "We found that individuals harboring the MDM4 SNP34091AC/CC genotypes had a significantly elevated risk for serous ovarian cancer (SOC) in general and high-grade serous ovarian cancer (HGSOC) in particular (SOC: OR = 1.18., 95 % CI = 1.01–1.39; HGSOC: OR = 1.25, CI = 1.02–1.53)." (PMID 26867771, 2016). "Given that we previously have found a SNP in the MDM4 3 ‘UTR (SNP34091) to be associated with increased risk of serous, and in particular high grade serous ovarian cancer, we performed subgroup analysis based on histology status with respect to del1581." (PMID 28158999, 2017). "Importantly, MDM4 nuclear localization and intra-tumor estrogen availability correlate with decreased platinum-sensitivity and apoptosis and predicts poor disease-free survival in high-grade serous ovarian carcinoma." (PMID 31547268, 2019).
squamous cell carcinoma (3 papers, 2017 to 2024). A carcinoma arising from squamous epithelial cells. "In cervical squamous cell carcinoma and endocervical adenocarcinoma (CESC) and ESCA, adenocarcinoma had a higher MDM4 mRNA expression compared to the squamous cell carcinoma." (PMID 38281029, 2024).
thymoma (3 papers, 2021 to 2024). A neoplasm arising from the epithelial cells of the thymus. "Meanwhile, the whole exome sequencing analysis (WES) result indicated that the MDM4 amplifified in this thymoma cells." (PMID 35070964, 2021). "However, we used the qPCR assay and IHC test to measure mdm4 levels in these 13 thymoma patients with autoimmune hepatitis/myocarditis, and discovered that mdm4 level was up-regulated." (PMID 35070964, 2021). "Immunohistochemistry indicated that thymoma cells were positive for MDM4." (PMID 34054730, 2021). "Results of WES showed that only one driver gene-MDM4 amplified 4 fold in 53.2% thymoma cells." (PMID 35070964, 2021). "We ever tested that mdm4/mdm2 heterodimers were down-regulated in thymoma patients without autoimmune hepatitis/myocarditis." (PMID 35070964, 2021).
brain cancer (2 papers, 2023). A primary or metastatic malignant neoplasm affecting the brain.
Breast invasive carcinoma (2 papers, 2016 to 2024). "In conclusion, we have herein demonstrated that ERα expression associates with MDM4 and MDM2 gene expression in primary breast invasive carcinoma samples." (PMID 26909605, 2016). "We observed that MDM4 and MDM2 mRNA expression was elevated in primary breast invasive carcinomas of luminal A and luminal B molecular subtypes, as compared to HER2-enriched, basal, and normal-like subtypes." (PMID 26909605, 2016). "In the present study, we utilized The Cancer Genome Atlas invasive breast carcinoma (TCGA BRCA) RNA-Seq gene expression dataset to analyze the expression of MDM4 and MDM2 mRNA in treatment-naive primary human breast invasive carcinoma samples." (PMID 26909605, 2016). "Using the Cancer Genome Atlas (TCGA) breast invasive carcinoma patient cohort, we have analyzed correlations between ERα status and MDM4 and MDM2 expression in primary, treatment-naïve, invasive breast carcinoma samples." (PMID 26909605, 2016).
Burkitt lymphoma (2 papers, 2021 to 2025). A rare form of malignant mature B-cell non-Hodgkin lymphoma.
dyskeratosis congenita (2 papers, 2020 to 2025). Dyskeratosis congenita (DC) is a rare ectodermal dysplasia that often presents with the classic triad of nail dysplasia, skin pigmentary changes, and oral leukoplakia associated with a high risk of bone marrow failure (BMF) and cancer. "Recently, a germline missense mutation in the MDM4 coding region has been described in a family that exhibited some dyskeratosis congenita (DC)-like phenotypic traits." (PMID 39940930, 2025).
liposarcoma (2 papers, 2013 to 2015). A usually painless malignant tumor that arises from adipose tissue. "Grade III staining (>51% positive MDM4 cells) was only observed in one de-differentiated liposarcoma (Tumour SE74)." (PMID 26095524, 2015).
maturity onset diabetes of (2 papers, 2022 to 2024). "MDM4 was positively linked to alpha–linolenic acid metabolism, linoleic acid metabolism, maturity onset diabetes of the young, nicotine addiction, and phototransduction." (PMID 36313991, 2022).
medulloblastoma (2 papers, 2021 to 2023). A malignant, invasive embryonal neoplasm arising from the cerebellum. "In cell lines of medulloblastoma origin, MDM2 showed the largest difference in dependency score with negative regulators PPM1D, USP7 and MDM4, ranked 6, 41 and 64, respectively." (PMID 34885154, 2021).
metastatic disease (2 papers, 2019 to 2020).
myeloid leukaemia (2 papers, 2012 to 2023). "Recent demonstration shows that MDM4 amplification in the bone marrow cells of FA patients confers greater fitness to the cells and yields clonal expansion preceding transformation to myeloid leukaemia." (PMID 37573408, 2023).
myocarditis (2 papers, 2021). Myocarditis is a condition that is characterized by inflammation of the heart muscle (myocardium). "The result indicated that the level of mdm4 was up-regulated in tumor tissues with autoimmune hepatitis and myocarditis comparing to the normal thymus tissue and tumor tissues without autoimmune disease." (PMID 35070964, 2021). "In contrast, more mdm4-positive cells were found in medulla regions for tumor tissues with autoimmune hepatitis and myocarditis." (PMID 35070964, 2021).
neutropenia (2 papers, 2020 to 2023). A decrease in the number of neutrophils found in the blood. "In humans, the MDM4 (p.T454M) mutation was identified in this family with neutropenia, bone marrow hypocellularity, early-onset tongue SCC, AML, and telomeres between the 1st and 10th percentiles in the younger generation." (PMID 32300648, 2020).